IL4 (interleukin 4)
Diseases named in the same sentence as IL4 in open-access papers (continued):
Sharing a sentence is not in itself a finding about the gene and the disease.
tumor (continued). "The pro‐inflammatory cytokines IL‐4 and IL‐6, produced either by host immune cells or by tumor cells themselves, are associated with tumor malignancy in patients and animal cancer models." (PMID 32485045, 2020). "The higher expression of interleukin IL-1β and IL-4 delineated a high-risk association with bone metastasis and tumor progression." (PMID 33112542, 2020). "The pro-tumor effect of IL-4 is associated with the up-regulation of anti-apoptotic molecule Bcl-2 and the weak down-regulation of the pro-apoptotic molecule Bax." (PMID 32655554, 2020). "The predicted postoperative survival curves based on the Cox model for serum IL-4 levels and age revealed independent effects: both a younger age and lower IL-4 levels were associated with a lower risk of postoperative tumor recurrence." (PMID 33255425, 2020). "In cancer, IL-4 has been associated with tumor aggressiveness, and IL-4 pathway blockade is currently investigated as anti-cancer strategy." (PMID 33042132, 2020). "Tumor-associated macrophages can be stimulated by IL-4, IL-10, or IL-13 and then migrate into tumor tissue, where they perform protumorigenic functions." (PMID 33292489, 2020). "A similar finding was observed in tumor-associated macrophages, in which IL-4 synergized with IL-10 to activate the UPR via STAT3." (PMID 32714202, 2020). "IL-4 can promote tumor growth by inducing cathepsin protease activity in tumor-associated macrophages." (PMID 33537234, 2020). "Once in the TME, macrophages are activated to tumor-associated macrophages (TAMs) through CSC-secreted factors such as IL4, TGF-ß and macrophage inhibitory cytokine 1 (MIC-1), which also inhibits the phagocytic activity of macrophages." (PMID 33059744, 2020). "Secretion of immunoregulatory cytokines such as IL‐4 leads to the induction of cathepsin protease activities in tumour‐associated macrophage, which then promotes pancreatic tumour growth." (PMID 32969187, 2020). "When analyzing systemic IL-10 and IL-4 in regards to clinicopathological data and overall survival, only IL-10 demonstrated to be significantly associated with increased tumor stage and distant metastases." (PMID 32298379, 2020). "More recently, ABCA1 and ABCG1 have been shown to play a role in interleukin 4 (IL-4) mediated macrophage activation in tumor-associated macrophages." (PMID 32647530, 2020). "It has been shown that cancer initiating cells inhibited T cell proliferation in vitro via their membrane-associated IL-4 and IL-4R, while blocking IL-4-impaired tumor growth and stimulating antitumor T cell effectors." (PMID 33233582, 2020). "Tumor-associated IL-4 can induce Th2 differentiation via STAT6 phosphorylation to directly inhibit T-cell cancer immunity." (PMID 31379876, 2019). "In particular, we found that local production of IL-4 at the tumor site is associated with increased infiltration of CD8+ T and CD4+ T cells, B lymphocytes and macrophages." (PMID 30909395, 2019). "Then, we likely suggested that on 21st day, the tumour-bearing group (21 W) was subjected to more intense effects of the inflammatory process, higher interleukin IL-4 are associated with increased levels of IL-6, TNF and INF in the W group." (PMID 30975087, 2019). "With respect to T cell-associated cytokines, TH2 cytokines (like IL-4, IL-5 and IL-13) were selectively elevated in tumor patients suggesting an immunosuppressed status in these patients." (PMID 30740106, 2019). "In a mouse breast cancer model, mice have been shown to develop IL-4-producing Th2 cells, which polarized tumor-associated macrophages (TAMs) to the M2 phenotype." (PMID 31366131, 2019). "Lastly, we found dysregulated amounts of IL-4 and IL-5 cytokines, and a concomitant increase in the number of tumor associated-macrophages (TAMs)." (PMID 31555258, 2019).
tumor (continued). "IL-4 has been previously related to VEGF as an important factor in the recruitment of tumor-associated macrophages (TAMs), which are known to promote angiogenesis, tissue remodeling and immunosuppression." (PMID 31419243, 2019). "We also explored different strategies in silico to elicit pro-inflammatory macrophage polarization when IL-4 levels are abnormally elevated, a feature often observed in the tumor microenvironment and associated negatively with patient survival." (PMID 31738746, 2019). "In contrast, Th2 cells, by secreting IL-4,-5,-6,-10, and -13, induce loss of T-cell-mediated cytotoxicity and enhance the tumor-promoting activities of macrophages (M2 polarization)." (PMID 31554173, 2019). "IL-4 and IL-13 were key players for activating tumor-associated macrophages and myeloid-derived suppressor cells that promoted tumor development." (PMID 30486830, 2018). "Expression of Il4, Il10 and Il13, which represent cytokines commonly associated with alternative macrophage activation, was undetectable in 4T1 tumours." (PMID 30054470, 2018). "The expression of IL-4 was significantly associated with tumor size, stage, lymphovascular invasion, and lymph node metastasis (p = 0.029, p = 0.040, p = 0.003 and p = 0.002, respectively)." (PMID 29315254, 2018). "Nevertheless, this effect needs to be tightly controlled as IL-4 is also active in fibrosis, tumor formation via tumor-associated macrophages, and also in atherosclerosis." (PMID 30177966, 2018). "Another pro-inflammatory cytokine IL-4, which is implicated in tumor promoting activities however, remained unaffected with DEN treatment compared to untreated normal." (PMID 28830415, 2017). "The IL-4 secreted by cancer cells is responsible for tumor-associated macrophages (TAM) polarization toward M2 macrophages inducing cathepsin activity." (PMID 28927416, 2017). "Tumor-associated macrophages (TAMs) are alternatively activated cells that are induced by interleukin-4 (IL-4)-releasing CD4+ T cells." (PMID 29197379, 2017). "In the tumor microenvironment, tumor-associated macrophages (TAMs) are “polarized” into M2 mononuclear phagocyte-like cells by various cytokines (IL-4, IL-10, and transforming growth factor β (TGF-β))." (PMID 28218682, 2017). "Data provided in this review demonstrate that most proinflammatory cytokines (IL-1, IL-4, IL-6) produced by either host immune cells or tumor cells themselves are associated with tumor malignancy in patients and animal cancer models." (PMID 28927416, 2017). "The secretion of the first molecule by cancer cells and cancer associated cells is a well know mechanism of tumor evasion, and IL-10 as well as IL-4 are potent immunosuppressive cytokines." (PMID 28331617, 2017). "It is also able to recruit NK cells to the tumor site, reactivate anergic tumor-infiltrating lymphocytes (TILs), inhibit regulatory T-cells and the secretion of IL-10, IL-4 and trasforming growth factor beta (TGFβ) by tumor associated macrophages." (PMID 28331617, 2017). "The expressed IL-4 induces T-cell anergy and loss of T-cell-mediated cytotoxicity leading to the promotion of tumor development and disease progression." (PMID 28927416, 2017). "Some mechanisms responsible for dysfunction of immune cells are directly mediated by factors produced by tumors, whereas others result from tumor-associated microenvironment, including IL-1β, IL-4, IL-6, IL-10, IFN-γ and TGF-β." (PMID 27391078, 2016). "Several markers have been reported to reflect the association of inflammation and tumor, such as interferon-gamma/interleukin-4 ratio and inflammation-based prognostic score based on CRP and albumin levels." (PMID 27125872, 2016). "As expected, NF-κB activation (as assessed by measuring IκB-α phosphorylation and expression levels of the representative Th2 cytokines IL-4 and IL-13) was significantly downregulated in sST2-expressing tumours compared with sST2-deficient tumours." (PMID 27882929, 2016).
tumor (continued). "Several studies have used malignant tumor cells genetically engineered to produce IL-4 and shown potent anti-tumor effects in vivo associated with inhibiting primary tumor burden." (PMID 27563494, 2015). "We next explored the effect of IL-4 from cancer cells on the composition and phenotypes of tumor-associated immune cells." (PMID 27563494, 2015). "When transplanted into IL-4 deficient mice, both parental Pam 212 and metastatic variant tumors demonstrated suppressed tumor growth." (PMID 26690220, 2015). "This ~10 fold increase in Arg1+ cells in the absence of a significant increase in CD11b+ cells suggests that IL-4 produced by tumor cells promoted M2 polarization of tumor associated myeloid cells in vivo." (PMID 27563494, 2015). "Although M2-like TAMs have been linked to enhanced tumorigenesis, this study shows that IL-4 production by cancer cells is associated with suppressed tumor growth and loss of metastatic potential as well as enhanced phagocytic behavior of TAMs." (PMID 27563494, 2015). "Our observations suggest that reduced primary tumor growth and suppression of metastasis is associated with M2-like TAMs induced by cancer cell-derived IL-4." (PMID 27563494, 2015). "IL-4 polarizes myeloid precursors towards a M2 phenotype, which is strongly associated with tumor associated MDSCs and express IL-10 to mediate their immune suppressive effects." (PMID 24733360, 2014). "The STAT3 pathway is more highly activated in response to several cytokines, including IL-1β, IL-4 and IL-10 in tumor-associated macrophages of the M2 phenotype than in M1 macrophages." (PMID 25198511, 2014). "iNKT-cell activation will also lead to IL-4 release causing the activation of CS-initiating B-1 cells to produce Hapten-Tumor IgM." (PMID 24949488, 2014). "The action of IL-4 during carcinogenesis is possibly linked with the presence and induced cellular activity of tumor-associated macrophages (TAM), which exhibit so-called M2 phenotypes that promote progression and cancer metastasis." (PMID 24278120, 2013). "Solid tumors are frequently infiltrated by tumor-associated macrophages (TAMs), which are driven by tumor and T cell derived cytokines (especially IL-4, IL-10, and IL-13) to acquire an “alternatively activated” M2 phenotype with pro-tumor properties." (PMID 23950747, 2013). "Researchers have recently shown that mice treated with vector constructs that were able to encode for interleukin-2 (IL-2), IL-4, or IL-12 cytokines presented a rapid and sustained tumor regression." (PMID 23443138, 2013). "IL4 increased the Cat S activity in tumor-associated macrophages, and we found it selectively upregulated Cat S (and Cat K) expression." (PMID 23786632, 2013). "IL4 pathway-associated genes that were differentially expressed with tumor progression and/or chemotherapy." (PMID 23451142, 2013). "It has been reported that interleukin-4 released from tumor cells attracts tumor-associated macrophages in the peritumoral tissue and induces cathepsin protease activity of macrophages to promote tumor growth and metastasis." (PMID 23737988, 2013). "Several publications, using a variety of murine tumor models, have identified IL-4 and TGFβ-dependent suppressive effects of tumor associated MDSCs." (PMID 23843936, 2013). "On the contrary, Th2 cells secrete IL-4 and enhance tumor progression in activating, for example, tumor-associated macrophages." (PMID 22949815, 2012). "Tumor-associated IL-4 also polarizes CD8+ T-cells to a “type 2” phenotype, leading to further compromised anti-tumor immunity." (PMID 24213139, 2011). "In contrast, IFN-γ, TNF-α, IL-5, IL-4, IL-2 and low amounts of IL-10 were produced upon stimulation with the tumor cell lines encoding the HPV16E7wt and HPV16E7V constructs." (PMID 21892941, 2011). "IL4 plays an established role in activating tumor-associated macrophages, and can be regulated by COX-2 activity." (PMID 21978392, 2011).
tumor (continued). "Tumor-associated macrophages (TAMs) are alternatively activated cells induced by interleukin-4 (IL-4)-releasing CD4+ T cells." (PMID 21939504, 2011). "Numerous preclinical studies have shown the potent anti-tumour activity of a monospecific cytotoxin composed of IL-4 linked to PE38." (PMID 19755995, 2009). "Further examination of CD8+ T-cell effector function revealed decreased production of cytokines associated with tumor growth, such as IL-4, an immunomodulatory and inflammatory cytokine, which has been shown in vitro to facilitate growth and propagation of HNSCC." (PMID 41431358, 2026). "Among these, IL-2 and TNF-α are especially relevant for T cell expansion and anti-tumor immunity, while IL-4 and IL-10, linked to Th2 responses, may play a lesser role in MM immune surveillance." (PMID 40948764, 2025). "IL-4 and IL-13 are the major cytokines transforming the tumor-associated macrophages (TAMs) to M2 macrophages that promote cancer progression and treatment resistance, and dupilumab reduces the pro-tumor phenotype of M2 macrophages." (PMID 39758935, 2025). "Furthermore, cytokines and signaling molecules such as IL-33, IL-6, GM-CSF, IL-4, and IL-10 orchestrate histone modification patterns in tumor-infiltrating MDSCs and tumor-associated macrophages (TAMs), enhancing their immunosuppressive functions." (PMID 41301911, 2025). "IL-4/IL-13 blockade has been linked to reduced tumor progression in various tumor models." (PMID 40843371, 2025). "Similarly, Ovatodiolide inhibits the expression of YAP-regulated M2 tumor-associated macrophage polarization factors, such as IL-4 and IL-13, altering the tumor microenvironment and thereby regulating the progression of CRC." (PMID 40612350, 2025). "M1 polarization is associated with macrophage-dependent tissue damage and tumor cell killing; therefore, reduced M2 induction resulting from the blockade of IL-4 and IL-13 could improve tumor response through macrophage polarization." (PMID 40507326, 2025). "In turn, TAMs may motivate the self-renewal and tumorigenic capacity of TCSCs, Using IL-4 and IL-13 cytokines, macrophages were successfully polarized towards M2-like tumor-associated macrophages (M2-like TAMs) in a co-culture experiment." (PMID 39776907, 2024). "IL-4 influences tumor-associated macrophage polarization in LC." (PMID 38361933, 2024). "Some literature suggests that although IL-4 has been previously linked to promoting tumors, it may also have anti-tumor effects, depending on its level and interactions with other immune regulatory factors." (PMID 38920620, 2024). "Moreover, tumor-associated macrophages protect tumor cells by an IL-13/IL-4-mediated increase of miR-660-5p, which was packed into exosomes and transferred to tumor cells." (PMID 39372215, 2024). "IL-4 is known to induce macrophages to polarize towards an M2-like phenotype, which is typically associated with wound healing and immunosuppression, thereby promoting tumor growth and metastasis through extracellular matrix remodeling and angiogenesis." (PMID 39125732, 2024). "IL-4, in association with IL-13, promotes tumor cell growth and proliferation in CTCL." (PMID 38607023, 2024). "Although low values of intracellular IL-10 were found in CD4+ T cells, the high values of that cytokine observed in the culture supernatant associated with high IL-4 suggest an anti-inflammatory profile (Th2) promotion by HPV oncogenes present in the transfected A549 tumor cells." (PMID 39599846, 2024). "IL-6 contributes to tumor promotion by the expansion and survival of malignant cells, neo‐angiogenesis, and inflammation, and it promotes expression of the T helper Th2 associated with IL-4." (PMID 38443899, 2024). "In addition, IL-4 can also regulate the phenotype of tumor-associated macrophages and indirectly enhance the metastatic capacity of cancer cells." (PMID 36980536, 2023). "Indeed, IL-4 produced by Th2, and tumor cells is crucial for the expansion of Tumor Associated Macrophages (TAMs)." (PMID 37760903, 2023).
tumor (continued). "On the one hand, the response can promote tumor dissemination and metastasis through the action of CD4+ Th2 effector cells, which regulate the pro-tumor properties of tumor-associated macrophages via IL-4 expression, and IL-4 is upregulated in many mouse and human tumors." (PMID 37429945, 2023). "In particular, tumour-associated macrophages (TAMs), such as M2 macrophages, promote tumour growth through angiogenesis, which is enhanced when Th2-associated cytokines such as IL-4 and IL-10 are upregulated." (PMID 36612301, 2023). "Of note, IL-4 is often associated with tumor where among its biological functions can promote proliferation and survival of cancer cells and its autocrine origin is an indicator of tumor aggressiveness." (PMID 36944188, 2023). "IL‐4 plays a critical role in tumour development, being associated with aggressiveness and metastasis potential, and most recent studies indicate that endogenous IL‐4 can favour resistance to apoptosis via IL4‐R signalling." (PMID 38117000, 2023). "IL-4-signalling induces alternative activation of macrophages to an M2 tumour-associated macrophage (TAM) phenotype with well-documented pro-tumoural functions in the tumour microenvironment." (PMID 37455828, 2023). "Th2 cell was proposed to promote tumor progression through the secretion of cytokines interleukin (IL)‐4, IL‐6, IL‐10, and IL‐13 to activate tumor‐associated M2 macrophages, and which was found to be a risk factor of male patients in SARC, LUAD, KIRP, PAAD, KIRC, and LIHC (HR > 1, Wald P < 0.05)." (PMID 35229456, 2022). "However, there are reports about the role of IL-4 in tumor growth, mediating increased proliferation and survival by promoting tumor-associated macrophage differentiation (TAM) towards an M2-like phenotype." (PMID 35269666, 2022). "Additionally, Th2 cytokines, particularly IL-4, are associated with a humoral response and have been shown to promote tumor cell proliferation and resistance to apoptosis." (PMID 35214172, 2022). "Generally, M1-polarized macrophages exert anti-tumor effects through eliminating and destroying phagocytosed tumor cells, while M2-like macrophages, activated by IL-4, IL-10 and IL-13, resemble tumor-associated macrophages (TAMs), which promote tumor progression though immunosuppressive functions." (PMID 35807802, 2022). "In vivo alterations of the tumor immune environment involved fewer protumorigenic tumor-associated macrophages (TAMs) and MDSCs due to the suppression of IL-4, IL-13, and CXCL1 expression, and elevated infiltration by antitumor CTLs and NK cells attracted by elevated CXCL9 and CXCL10 levels." (PMID 35499071, 2022). "Moreover, therapeutic bacteria carrying eukaryotic plasmids encoding cytokines such as IL-4 and IL-18, and angiogenesis inhibitors such as endostatin and thrombospondin all resulted in retardation of tumor growth and prolonged survival of tumor-bearing mice." (PMID 36276157, 2022). "The central role of IL4 signaling in MAMs was confirmed by high-resolution intravital imaging of the lung in mice at the time of metastatic seeding, which showed reduced physical interaction between tumor cells and IL4rα-deficient macrophages." (PMID 36077870, 2022). "Enhanced IL-4 secretion of cancer cells could also be involved in tumor-associated macrophages (TAM)-induced tumor growth and metastasis." (PMID 35203944, 2022). "Moreover, CD8+IL-4+ and CD4+IL-4+ T cells had positive associations with tumor size and stage of the disease." (PMID 36376825, 2022). "However, there is evidence, that IL4–secreting Th2 cells, inhibit proliferation of cytotoxic T cells and induce an M2 phenotype in tumor-associated macrophages, promoting tumor cell growth and invasion." (PMID 36700232, 2022).